TRBV13 (T cell receptor beta variable 13)
Description:
V region of the variable domain of T cell receptor (TR) beta chain that participates in the antigen recognition. Alpha-beta T cell receptors are antigen specific receptors which are essential to the immune response and are present on the cell surface of T lymphocytes. Recognize peptide-major histocompatibility (MH) (pMH) complexes that are displayed by antigen presenting cells (APC), a prerequisite for efficient T cell adaptive immunity against pathogens. Binding of alpha-beta TR to pMH complex initiates TR-CD3 clustering on the cell surface and intracellular activation of LCK that phosphorylates the ITAM motifs of CD3G, CD3D, CD3E and CD247 enabling the recruitment of ZAP70. In turn ZAP70 phosphorylates LAT, which recruits numerous signaling molecules to form the LAT signalosome. The LAT signalosome propagates signal branching to three major signaling pathways, the calcium, the mitogen-activated protein kinase (MAPK) kinase and the nuclear factor NF-kappa-B (NF-kB) pathways, leading to the mobilization of transcription factors that are critical for gene expression and essential for T cell growth and differentiation. The T cell repertoire is generated in the thymus, by V-(D)-J rearrangement. This repertoire is then shaped by intrathymic selection events to generate a peripheral T cell pool of self-MH restricted, non-autoaggressive T cells. Post-thymic interaction of alpha-beta TR with the pMH complexes shapes TR structural and functional avidity.
Synonyms: TCRBV13S1; TCRBV23S1A2T
Gene: T-cell receptor variable (V) gene on chromosome 7 (142,535,809 to 142,536,292, forward strand). Ensembl gene ENSG00000276405.
Subcellular location: Cell membrane
Gene Ontology:
Biological process: cell surface receptor signaling pathway
Cellular component: plasma membrane
Homologues: Orthologues: mouse Trbv12-2 (56% identical), mouse Trbv12-1 (55% identical). Paralogues in human: TRBV5-5 (55% identical), TRBV5-1 (54% identical), TRBV9 (54% identical), TRBV5-6 (53% identical), TRBV5-3 (51% identical), TRBV5-7 (51% identical), TRBV5-4 (50% identical), TRBV11-2 (45% identical), TRBV11-1 (44% identical), TRBV11-3 (43% identical), TRBV7-7 (42% identical), TRBV7-2 (41% identical), and 39 more.
Diseases named in the same sentence as TRBV13 in open-access papers:
TRBV13 is named in the same sentence as 5 diseases in open-access papers, as found by Europe PMC text mining. Sharing a sentence is not in itself a finding about the gene and the disease. The quoted sentences say what the papers report.
autoimmune thyroiditis (1 paper, 2023). "An increase in the level of T cells expressing TRBV13 is also associated with the progression of autoimmune thyroiditis." (PMID 36751634, 2023).
experimental autoimmune encephalomyelitis (1 paper, 2025). An autoimmune demyelinating disease of the central nervous system that is produced experimentally in animals by the injection of homogenized brain or spinal cord in Freund's adjuvant. "In the mice initiated with myelin oligodendrocyte glycoprotein (MOG)-induced experimental autoimmune encephalomyelitis (EAE), TRBV13-2 is preferentially used in the TCRβ gene of MOG-specific T cells." (PMID 41516289, 2025).
infection (2 papers, 2022 to 2024). The state of being infected such as from the introduction of a foreign agent such as serum, vaccine, antigenic substance or organism. "Quantifying and visualizing the number of cells using a given germline pairing revealed certain V genes dominated the repertoire across multiple mice in different infection conditions, such as TRBV13-1, TRBV19, and TRBV29." (PMID 35185882, 2022).
TRBV13 also shares sentences with these, for which no sentence is quoted: Autoimmunity (1 paper); COVID-19 (1).